LINC01592 (long independently transcribed non-coding RNA 1592)
Gene: Long non-coding RNA gene on chromosome 8 (68,852,582 to 69,254,715, reverse strand). Ensembl gene ENSG00000253658.
Diseases named in the same sentence as LINC01592 in open-access papers:
LINC01592 is named in the same sentence as 3 diseases in open-access papers, as found by Europe PMC text mining. Sharing a sentence is not in itself a finding about the gene and the disease. The quoted sentences say what the papers report.
esophageal cancer (1 paper, 2025). A primary or metastatic malignant neoplasm involving the esophagus. "These exosomes carry LINC01592 into esophageal cancer (EC) cells, where LINC01592 directly binds to E2F6 and promotes E2F6 entry into the nucleus." (PMID 41294803, 2025).
LINC01592 also shares sentences with these, for which no sentence is quoted: chlamydia (1 paper); tumor (1).